MMP13 (matrix metallopeptidase 13)
Diseases named in the same sentence as MMP13 in open-access papers (continued):
Sharing a sentence is not in itself a finding about the gene and the disease.
cancer (continued). "MMP-13 is an interstitial collagenase (also known as collagenase 3) and is overexpressed in various cancers and in cancer stromal cells." (PMID 35805035, 2022). "This review summarises the current understanding of the regulation of MMP-13 production and discusses the actions of MMP-13 in cancer progression and metastasis." (PMID 35805035, 2022). "In cancer, the tight control of MMP-13 production and activity is disrupted by intrinsic or extrinsic mechanisms." (PMID 35805035, 2022). "Recent studies have also reported the regulation of MMP-13 expression in cancer by other effectors, such as chemokines and endogenous enzymes." (PMID 35805035, 2022). "The exosome-activated mCAFs upregulate the activity of genes for MMP-1, MMP-2, MMP-7, MMP-8, MMP-13 and MMP-14 that are associated with cancer growth and progression." (PMID 34837514, 2022). "Based on this explanation, it was stated that the inhibition of the MMP12 and MMP13 activities correlated with the inhibition of cancer cell growth." (PMID 36106139, 2022). "As an interstitial collagenase that can cleave not only collagens but also a range of other ECM components, MMP-13 is overexpressed in various cancers and plays multiple roles in cancer development, progression and metastasis." (PMID 35805035, 2022). "Despite the critical involvement of MMP-13 in cancer progression and metastasis, the precise mechanisms of its regulation and actions are still not fully understood." (PMID 35805035, 2022). "The high expression of MMP-13 has been reported to be commonly upregulated in most of the cancer microenvironments, and increased stromal MMP-13 is important for promoting cancer invasion and angiogenesis." (PMID 34589582, 2021). "Only low level of MMP-13 expression was seen in benign breast lesions (8.8% in epithelial component and 2.2% in stromal fibroblasts), while high level of MMP-13 expression was noted in malignant tumors, mainly grade II or III." (PMID 34452576, 2021). "MMP-13 is expressed in a broad range of primary malignant tumors and has been emerged as a novel biomarker." (PMID 34452576, 2021). "Although MMP13 enhances the invasive capacity of cancer cells, the function of MMP13 in trophoblast cells remains largely undetermined." (PMID 33513878, 2021). "Conclusively, on the basis of positive expression of MMP-13 in majority of high-grade malignant tumors and low expression of detectable MMP-13 in few benign lesions, a possible role can be proposed for MMP-13 in the tumoral process and metastasis." (PMID 34452576, 2021). "All three tested groups were characterized by downregulation of MMP13, a protein involved in the ECM breakdown, and upregulation of MYCL, which is associated with cancer susceptibility as well as metastasis, prognosis, and adverse survival." (PMID 34579743, 2021). "The results of PPI demonstrated that the five TFs were tightly associated with many critical cancer related factors or pathways, such as SMAD4, MMP13, IL-5, IL-2, CYP2E1, CCNE1 and CDH1." (PMID 34405021, 2021). "MMP3 and MMP13 are matrix metalloproteinases which degrade extracellular matrix proteins and can also facilitate cancer cell metastasis to the lungs." (PMID 33777801, 2021). "In U251 glioma cancer cells, Rh2 (0.1mg/mL) displayed anti-metastatic effects mediated by regulation of Akt signaling pathways and reduced MMP-13 expression." (PMID 33671187, 2021). "MMP-13 (collagenase-3) has important roles in cancer invasion, metastasis, growth regulation, immune evasion, apoptosis, and angiogenesis." (PMID 34452576, 2021). "Despite the general notion that collagenases (MMP1, MMP8 and MMP13) are key players in cancer biology, relatively little is known about collagenases in PDAC." (PMID 32325664, 2020). "Zn level was not considered in previous studies investigating association of MMP-1, MMP-2, MMP-7, MMP-13 and MT2A polymorphism with cancer risk." (PMID 32765800, 2020).
cancer (continued). "MMP‐3 and MMP‐13 are proteolytic enzymes involved in the degradation of ECM around invasive cancer cells." (PMID 33040485, 2020). "MMP1, MMP9, MMP10, MMP11, and MMP13 were almost universally upregulated across all cancers, with significant (p < 0.05) fold change (FC > 2) in ten of fifteen cancers." (PMID 31200666, 2019). "Collagenases, MMP1 and MMP13, were significantly altered in 11 cancer types and 12 cancer types, respectively (p = 5E-05 to 1E-77)." (PMID 31200666, 2019). "MMP11 and MMP13 expression was dramatically higher in most cancer types compared to tissue matched controls." (PMID 31200666, 2019). "Increasing LPP1 expression in cancer cells attenuated the regulatory effects from stromal cells on MMP-13 production." (PMID 31534541, 2019). "The knockdown of YB-1 protein in this study has shown some promising properties by reducing the proliferation of cancer cells, interference with cancer cell cycle, inhibiting the cancer cell migration in vitro; in addition to the influence on MMP13 expression." (PMID 29320405, 2018). "In order to determine if MMP13 participates in ETV4-regulated cancer cell properties, we repressed MMP13 in the ETV4-overexpressing MMT cell line." (PMID 29996935, 2018). "The levels of hsa-miR-375 regulates the expression of MMP13, therefore promoting increased metastatic behavior and cancer aggressiveness in esophageal SCC26." (PMID 29330429, 2018). "In fact, our results demonstrated that, except MMP-7, antcin-H also inhibited other MMP gene expressions, such as MMP-2, MMP-3, and MMP-13, which play critical roles in cancer cell invasion." (PMID 29234409, 2017). "To determine the relationship between MMP‐13 and VM, we examined the expression of MMP‐13 and its relationship with VM formation in clinical cancer cases." (PMID 28766880, 2017). "And FLIP, FGF2, SULF2 and MMP13 are known to be overexpressed in various cancers and downstream of hnRNPK." (PMID 28423622, 2017). "Overexpression of MMP1, MMP2, MMP3, MMP7, MMP9, and MMP13 correlates with worse outcomes in cancer patients." (PMID 27908290, 2016). "We further demonstrated that matrix metalloproteinase 13 (MMP13) played an important role in CCR4-mediated cancer cell invasion, which is up-regulated by ERK/NF-κB signaling." (PMID 27356745, 2016). "These networks are interconnected with a subnetwork of genes that are associated with cancer progression, such as COX2, TGFβ, CCL2, CXCL2, MMP9, and MMP13." (PMID 26831400, 2016). "The objective of the present study was the identification of new NZIs selective toward MMP-2 and MMP-13, which are involved in cancer development." (PMID 27782083, 2016). "Some of them have been reported to be cancer-associated genes such as CDC25A, CDKN1A, MMP1, MMP13 and SOX4." (PMID 27863388, 2016). "We then examined the influence of EGF on MMP9 transcription as well as on the transcription of additional MMPs (MMP-1, MMP-2, MMP-3, MMP-7, MMP-10, MMP-13, MMP14, MMP15) and of CD44, a cell adhesion glycoprotein implicated in EMT and cancer metastasis." (PMID 26084289, 2015). "Our results therefore suggest that RKIP suppresses metastasis by specifically targeting MMP13 to prevent spreading of cancer cells into the draining lymph nodes." (PMID 26308852, 2015). "Together, our findings indicate that RKIP inhibits cancer cell invasion, in part, via MMP13 inhibition." (PMID 26308852, 2015). "Based on our previous observations, we noted that the expression of Mmp3, Mmp10, and Mmp13 was dramatically increased from inflammation to cancer, particularly during acute inflammatory stage (~200-fold increase)." (PMID 25742789, 2015). "Our data indicate that MMP-13 knockdown completely blocked cancer cell invasiveness to lung, suggesting that MMP-13 is a necessary mediator of Pit-1 induction of breast metastasis to lung." (PMID 25527274, 2014).
cancer (continued). "MMP-13 is involved in the initiation and progression of multiple biological events required for cancer cell progression such as metastasis, invasion, and proteolytic digestion, due to its ability to digest and degrade components of the extracellular matrix." (PMID 24599080, 2014). "Among the MMPs, MMP-13 is up-regulated by oncogenic proteins and activated in various cancers involving the lung, breast, prostate gland, and colon." (PMID 24599080, 2014). "MMP13 in particular has widely been found to promote cancer pathology, but a few emerging reports including this one find an apparently protective role for MMP13 in cancer and other diseases under some conditions." (PMID 24010522, 2013). "Epithelial cells in different types of human SCCs express both MMP-13 and uPA, and it would be interesting to examine this cancer type for a molecular and phenotypic overlap between the two proteases MMP-13 and uPA." (PMID 21326869, 2011). "Metalloproteinases (MMP)-13 is expressed in a broad range of primary malignant tumours and it is emerging as a novel biomarker." (PMID 22032644, 2011). "MMP-13 has been well documented in many aggressive cancers, but its expression is most often seen only in the invading front of tumors." (PMID 20649989, 2010). "High levels of MMP-13 in both cancer cells (p < 0.010) and peritumoral fibroblasts (p = 0.002), significantly correlated with the levels of TIMP-1 protein in the same specimens." (PMID 18373849, 2008). "Since MMP13 is upregulated concomitantly with the onset of cancer cell dissemination in the MMTV-PyMT model, we determined the metastatic burden in the lungs from end-stage MMTV-PyMT;Mmp13+/+ and MMTV-PyMT;Mmp13−/− mice using a morphometric approach." (PMID 18698413, 2008). "The expression of MMP-13 in cancer cells correlated with the MMP-13 expression in the peritumoral fibroblasts." (PMID 18373849, 2008). "It is possible that MMP13 plays both promoting and inhibiting roles during cancer progression, resulting in a neutral net effect in its absence in the MMTV-PyMT model." (PMID 18698413, 2008). "High levels of MMP-13 expression both in the cancer cells (p = 0.0008) and the neighboring fibroblasts (p = 0.0001) negatively correlated with OS." (PMID 18373849, 2008). "Instead, we noted that MMP-13, both in cancer cells and peritumoral fibroblast cells, correlated with TIMP-1 and TIMP-2 (to a lesser extent)." (PMID 18373849, 2008). "In the osteoblasts_Gapd2 subpopulation, pathways such as proteoglycans in cancer (Col1a1, Col1a2, Hcls1, Hif1a, Stat3, Vav1), IL-17 signaling (Mmp13, Mmp3, S100a9, Ccl7, Cebpb), and ECM–receptor interaction (Col11a2, Col1a1, Ibsp, and Tnn) were activated (p < 0.05)." (PMID 41459160, 2025). "A recent study showed that MMP13 is often overexpressed across cancer and predicts poor prognosis." (PMID 40552117, 2025). "Moreover, recent findings suggest that MMP-13 plays an important role in cancer progression and metastasis." (PMID 41471689, 2025). "In this context, there is evidence that inhibition of MMP-13 may promote cancer cell death by inducing ferroptosis." (PMID 41471689, 2025). "Furthermore, human MMP13 production increased in 10 kPa compared to soft controls in co–cultures across all cancer types." (PMID 39211033, 2024). "The role of MMP13 in cancer progression and metastasis is evident." (PMID 37090055, 2023). "In addition to known cancer-associated variants, we identified P/LP variants in the novel candidate cancer genes SF3B4, FMN2, and MMP13 (class 4)." (PMID 37377903, 2023). "This suggests that once the initial stages of invasion have occurred, cancer cells and fibroblasts may upregulate β6 and MMP13, respectively, to support invasion at later stages of disease." (PMID 36864079, 2023). "We next evaluated the effect pattern of MMP13 in pan-cancer." (PMID 38066539, 2023).
cancer (continued). "The discovery in this study that galectin-3 increases the secretion of Cathepsin-B, MMP-1, and MMP-13 by cancer cells suggests that increasing the secretion of proteases is probably one of the mechanisms behind galectin-3-mediated cancer promotion reported in many previous studies." (PMID 37055381, 2023). "Interestingly, HIF-1α and MMP-13 were localized in cancer cells and exosomes when cells were exposed to hypoxia." (PMID 38069210, 2023). "MMP-1 and MMP-13 are primarily responsible for ECM degradation in cancer progression." (PMID 37055381, 2023). "This implies that once the initial stages of invasion have occurred and the β6/MMP13 expressing-myoepithelial cell layer is lost, cancer cells may upregulate β6 and MMP13 expression to facilitate their invasion, alongside MMP13 positive myofibroblasts." (PMID 36864079, 2023). "As in cancers that grow in bone, osteocyte apoptosis and dysregulation of the dendritic network were observed, accompanied by upregulation of several genes associated with bone resorption (ACP5, CTSK, ATP6V0D2, and MMP13) in osteocytes." (PMID 37174109, 2023). "TQ has the ability to downregulate NF-κB, interleukin-1β, tumor necrosis factor alpha, cyclooxygenase-2 (COX-2,) matrix metalloproteinase 13 (MMP-13), prostaglandin E2 (PGE2), the interferon regulatory factor, which are associated with inflammation and cancer development." (PMID 38248312, 2023). "Additionally, the STRING database shows that COL10A1 closely interacts with several proteins, of which some are famously described as potent promoters of cancer stem cells and mesenchymal transformation, such as MMP13, SOX9, and RUNX2." (PMID 36267978, 2022). "Little is known about whether MMP-13 appearance/overexpression in cancer and stromal cells influences the activity or function of cell surface molecules, such as cell adhesion and signalling proteins." (PMID 35805035, 2022). "Future research will help to gain further insights into the role and actions of MMP-13 in cancer and determine whether MMP-13 represents an effective therapeutic target for this disease." (PMID 35805035, 2022). "The invasive effects of MMP13 on cancer cells can be mediated through six novel targets, including the inactivation of chemokine C-C motif ligand 2 (CCL2) and CCL7, activation of platelet-derived growth factor-C (PDGF-C) and cleavage of SAA3, osteoprotegerin (OPG), CutA and antithrombin III." (PMID 35884405, 2022). "Much also remains unknown about the possible coordination of MMP-13 action with other MMP family members during cancer pathogenesis." (PMID 35805035, 2022). "Differentiated osteoblasts induce invasive stimuli in BC cells using MMP13 mRNA and protein, which in turn are induced in the osteoblasts by the cancer cells through soluble factors, including oncostatin M, and the acute-response apolipoprotein serum amyloid A-3 (SAA3)." (PMID 35884405, 2022). "The present study suggests that RUNX2-mediated MMP13 expression controlled by ABL may lie downstream of not only cancer biology but also other physiologic pathways." (PMID 34136397, 2021). "Moreover, genomic amplification of MMP13 and COL1A1 showed association with individual cancer stage." (PMID 33014334, 2020). "Interestingly, several genes associated with cancer cells invasion were downregulated upon HPSE knockdown, including MMP1, MMP7, MMP10, MMP13, and CEACAM6." (PMID 31001480, 2019). "In fact, MMP13 has the same behavior as ETV4 in these cancer cells but is less potent." (PMID 29996935, 2018). "MMP13 has a role in different kind of cancer and is overexpressed in a variety of malignant tumors." (PMID 29996935, 2018). "In particular, MMP-13 contributes to bone lysis and metastasis in breast and prostate cancers." (PMID 29510576, 2018). "Moreover, cell proliferation, migration, invasion, anchorage-independent growth, and in vivo tumorigenicity were assayed using models of mammary epithelial and cancer cells in which the expression of MMP13 and/or ETV4 is modulated." (PMID 29996935, 2018).
cancer (continued). "Thus, similarly to ETV4, but with a weaker effect, MMP13 is an inducer of cancer cell proliferation, migration, and invasion." (PMID 29996935, 2018). "To that regard and following RSU-1 silencing, we tested the mRNA expression of Urokinase Plasminogen Activator (UPA), a known protease involved in cancer progression and metastasis, as well as that of metalloproteinase-13 (MMP-13) known to be involved in collagen I degradation." (PMID 28423706, 2017). "Besides, as FGF2 is an in vivo modulator of matrix metallopeptidase 13 (MMP-13) expression in malignant tumors, a significant decrease in the level of MMP-13 protein was also observed in miR-195 overexpressing cells." (PMID 28740507, 2017). "In addition, YB1 binds to Matrix metalloproteinase‐13 (MMP‐13) promoter AP‐1 site and represses MMP‐13 expression, which is essential for cancer invasion." (PMID 27047740, 2016). "MMP10 and MMP13 can degrade the extracellular matrix and promote cancer metastasis and progression." (PMID 27172796, 2016). "p38α also induces the expression of MMP1, MMP2, MMP9 and MMP13 in other types of cancer." (PMID 27286263, 2016). "MMP13 could be produced by various types of cancer cells and serves as a critical regulator of metastatic process in human malignancies." (PMID 27356745, 2016). "Of all the differentially expressed genes, secreted signaling proteins Tgfb2, Il-6, Cxcl1, and Ctgf and metallopeptidases Mmp13, Adamts4, and Adamts5 were of particular interest, as these genes have previously been shown to play a role in regulating cancer migration and invasion and bone remodeling." (PMID 27600237, 2015). "Erk2 may antagonize the inhibitory effect of RKIP on cancer cell invasion by promoting increased expression of MMP13." (PMID 26308852, 2015). "Mmp13 has also been shown to regulate cancer-induced osteolysis." (PMID 27600237, 2015). "Taken together, these data suggest that endogenous nuclear β-catenin associates with chromatin containing MMP13 promoter, and nuclear β-catenin translocation may activate MMP13 to enhance cancer cell invasiveness in BC cells." (PMID 26369384, 2015). "MMP13 is produced by various types of cancer cells and degrades collagen types I, II and III." (PMID 25609201, 2015). "This suggests that MMP-13 may play a key role in orchestrating the early signaling events required for cancer cell invasion." (PMID 26193700, 2015). "MMP-1 and MMP-13 should continue to be looked upon as targets in cancer and COPD therapy." (PMID 25664615, 2015). "It is possible that RKIP inhibits cancer cells invasion by decreasing MMP13 expression." (PMID 26308852, 2015). "To further generalize our findings, we used LPS to stimulate murine macrophages (RAW264.7) to imitate inflammation and measured Mmp3, Mmp10, and Mmp13 expression over time; the mRNA levels were significantly increased, indicating that these three genes are upregulated in inflammation-cancer link." (PMID 25742789, 2015). "A potential role for MMP-13 as a marker for CRC was studied, revealing increased MMP-13 expression with advanced cancer stage and nearly eight-fold increased risk of post-operative relapse compared to those without MMP-13 overexpression." (PMID 24518611, 2014). "Moreover, verrucarin A was able to inhibit expression of the SRC-3 target genes MMP2 and MMP13 and attenuated cancer cell migration." (PMID 24743578, 2014). "In human cancer upregulation of MMP13 contributes to metastasis onset." (PMID 24658133, 2014). "The important role of another MMP family member, MMP-13, has been demonstrated in human cancer." (PMID 21726449, 2011). "In both skin SCC and skin wound healing, epithelial cells (cancer cells and keratinocytes) express MMP-13 and uPA and in mice MMP-13 appears to be the main collagenase involved in epidermal keratinocyte migration across a collagen- and fibrin-rich provisional matrix in vitro." (PMID 21326869, 2011).